ZSCAN5C (zinc finger and SCAN domain containing 5C)
Description:
May be involved in transcriptional regulation.
Synonyms: ZSCAN5CP; ZNF495C
Tractability: No criterion of Open Targets' tractability assessment is met for any kind of drug.
Gene: Protein-coding gene on chromosome 19 (56,202,273 to 56,209,461, forward strand). Ensembl gene ENSG00000204532.
Subcellular location: Nucleus
Subcellular location (Human Protein Atlas): Nuclear speckles
Gene Ontology:
Molecular function: DNA-binding transcription factor activity, RNA polymerase II-specific; RNA polymerase II cis-regulatory region sequence-specific DNA binding
Biological process: regulation of transcription by RNA polymerase II
Cellular component: nucleus
Genetic constraint (gnomAD): Loss-of-function variants: 3 observed, 7.79 expected, observed/expected ratio (o/e) 0.39, 90% interval 0.17 to 1. That is too few expected variants to judge how well the gene tolerates losing a copy. Missense variants: 323 observed, 307.23 expected, observed/expected ratio (o/e) 1.05, 90% interval 0.96 to 1.15. Synonymous variants: 112 observed, 119.48 expected, observed/expected ratio (o/e) 0.94, 90% interval 0.8 to 1.1.
Homologues: Orthologues: chimpanzee ZSCAN5C (97% identical), mouse Zscan5b (36% identical), rat Zscan5b (36% identical), Drosophila melanogaster CG12391 (15% identical), zebrafish ovol1a (12% identical), Drosophila melanogaster hb (11% identical), zebrafish plagl2 (11% identical), zebrafish ovol1b (10% identical), Caenorhabditis elegans lin-48 (9% identical), zebrafish plagx (9% identical), Caenorhabditis elegans hbl-1 (8% identical), Caenorhabditis elegans Y5F2A.4 (7% identical). Paralogues in human: ZSCAN5A (84% identical), ZSCAN5B (76% identical), ZKSCAN2 (27% identical), ZSCAN29 (26% identical), ZSCAN32 (26% identical), ZNF174 (25% identical), ZNF18 (24% identical), ZNF202 (23% identical), ZNF496 (23% identical), ZNF274 (22% identical), ZNF446 (19% identical), ZNF444 (18% identical), and 17 more.